MIR548F5 (microRNA 548f-5)
Synonyms: hsa-mir-548f-5; MIR548F-5; MIRN548F5
Gene: MicroRNA gene on chromosome X (32,641,474 to 32,641,559, reverse strand). Ensembl gene ENSG00000221348.
Diseases named in the same sentence as MIR548F5 in open-access papers:
MIR548F5 is named in the same sentence as 1 disease in open-access papers, as found by Europe PMC text mining. Sharing a sentence is not in itself a finding about the gene and the disease.
MIR548F5 shares sentences with these, for which no sentence is quoted: tumor (1 paper).